CTLA4 (cytotoxic T-lymphocyte associated protein 4)
Diseases named in the same sentence as CTLA4 in open-access papers (continued):
Sharing a sentence is not in itself a finding about the gene and the disease.
tumor (continued). "The unexpected clinical success of immunotherapy by targeting the immune system using immune checkpoint inhibitors like anti-PD1- and/or anti-CTLA4 antibody in different tumor entities has proven the importance of tumor immune cell interactions within the tumor microenvironment." (PMID 30779021, 2019). "Overall, we found our results to indicate that on average (and for individual cases) anti-PD-1 administered first followed by anti-CTLA-4 (blue) produced a greater effect on tumor response than anti-CTLA-4 first followed by anti-PD-1 (red), consistent with clinical results." (PMID 31375756, 2019). "Recently, cytotoxic T-lymphocyte-associated protein 4 (CTLA4), programmed death-1 (PD-1) and programmed death-ligand 1 (PD-L1) have been shown to be highly promising targets for modulating the interaction of immune cells and tumor cells." (PMID 31762828, 2019). "Thus, PD1 inhibitors (nivolumab and pembrolizumab) and CTLA4 inhibitors (ipilimumab) enhance anti-tumor immune response delaying tumor growth and facilitating tumor rejection." (PMID 31649883, 2019). "Indeed, the ability of anti-CTLA-4 therapy to enhance anti-tumor immunosurveillance has led to the approval of Ipi as a drug against advanced melanoma." (PMID 31568531, 2019). "Blockade of the PD-L1/PD1 axis prevents inhibition of T-cell function, while blockade of CTLA-4 induces expansion of tumor reactive T-cells and there is strong interest in identifying small-molecule-immunotherapy combinations to increase the proportion of responses to checkpoint blockade." (PMID 31779705, 2019). "Using mice bearing partially immunogenic tumors, the Allison group showed that CTLA4 blockade could enhance the endogenous anti-tumor response after tumor implantation." (PMID 32039024, 2019). "In similar fashion within the confines of the tumour, CTLA-4 fosters immunosuppression through the induction and differentiation of Treg cells along with the upregulation of IL-10 and IDO (indoleamine-2,3-dioxygenase) by means of a CD80 and CD86 counter signaling approach." (PMID 30893948, 2019). "Finally, we identify BayK8644 as a potent TMEM176B inhibitor that promotes CD8+ T cell-mediated tumor control and reinforces the antitumor activity of both anti-CTLA-4 and anti-PD-1 antibodies." (PMID 31085177, 2019). "To date, the most prominent examples have been antibodies that block the inhibitory immune checkpoint proteins cytotoxic T lymphocyte antigen 4 (CTLA-4), and PD-1 that are expressed predominantly on T cells, or PD-L1 that is expressed on different immune cells as well as aberrantly on tumor cells." (PMID 30941312, 2019). "Herein, we demonstrated that the combination of an archaeosome adjuvanted vaccine with two checkpoint inhibitors (anti-CTLA-4 and anti-PD-1) could enhance survival and reduce tumor growth compared to either treatment alone." (PMID 31771150, 2019). "Interestingly, in a previous study, when we evaluated MS–OVA (enc) in combination with anti-PD-1, anti-CTLA-4 and anti-PD-L1 therapy, we were able to protect 70% of mice beyond 100 days after the tumor challenge, longer than obtained in the current study." (PMID 31771150, 2019). "Furthermore, accumulation of CTLA-4-positive Treg cells in the tumor microenvironment increases immunosuppressive function in the milieu around the tumor cells." (PMID 31581738, 2019). "Although repeated treatment with anti-CTLA-4 and anti-PD-1 as single-agent could reduce tumor growth, significant tumor eradication was only observed when the HDACis was combined with the immunotherapy treatment." (PMID 31067680, 2019). "In addition, anti-CTLA4 or anti-PD-L1 have been shown to enable the memory of the immune system to recognise tumour antigens." (PMID 30678059, 2019). "Tumour cell‐intrinsic CTLA4 expression provides us new therapeutic target for NSCLC treatment." (PMID 30378264, 2019).
tumor (continued). "In recent times, more than four checkpoint antibody inhibitors targeting PD-1, PDL-1, and CTLA-4 have been commercialized, and these checkpoint blockers are rapidly becoming a promising cancer treatment with significant anti-tumor responses and limited side effects." (PMID 31864288, 2019). "In a murine model, the neutralization of soluble NKG2D ligands such as MICA and MICB with mAb B10G5 was effective against prostate carcinoma and metastasis, leading to the enhanced NK cell infiltration in the tumor parenchyma, and improving CTLA-4 blockade therapy." (PMID 32038612, 2019). "In addition, the combination of IT SS1P and IP anti-CTLA-4 significantly prolonged the survival of AE17-M tumor-bearing mice compared to control groups." (PMID 30621280, 2019). "qPCR assay was used to evaluate the expression of c-MET and CTLA-4 in primary NSCLC tumor tissues." (PMID 29187584, 2019). "Compared to single treatments, a combination of intradermal DNA vaccination (ovalbumin or gp100 plasmid adjuvanted with IL12 plasmid) and immune checkpoint CTLA-4/PD-1 blockade resulted in a significant delay in tumor growth and prolonged survival of treated mice." (PMID 31150505, 2019). "Cell surface expression of immune checkpoint proteins including CTLA-4, PD-1, and PD-L1 may enable the tumor to escape the immune response or to prevent activation of T lymphocytes." (PMID 31192129, 2019). "Furthermore, when PLX397 was combined with anti-PD-1 and anti-CTLA4 antibodies tumor expansion was completely blocked and even regressed compared to a 50% limit in tumor growth with checkpoint blockade alone compared to vehicle control." (PMID 31138333, 2019). "This may explain why stage III and IV MSI-H CRC did not manifest a better survival, it might be because the immune system has completely lost the fight against tumor cells who overexpressed PD-1 and CTLA-4, and then metastasis began." (PMID 31639018, 2019). "Additionally, preclinical studies have shown that targeting CTLA-4 on T-reg cells conferred minimal tumor protection in comparison to when antibody bound to CTLA-4 on both T-eff and T-reg compartments in vivo." (PMID 30941125, 2019). "In contrast to YUMM1.1 tumors, there was a significant extension of survival of YOVAL1.1-bearing C57BL/6 mice co-treated with anti-PD-1 and anti-CTLA-4 therapy compared to isotype controls, with median survival of 57 days versus 40 days post tumor inoculation, respectively." (PMID 30718660, 2019). "Moreover, secreted factors from tumor cells also increase the expression of programmed cell death 1 ligand (PD-L1) in monocytes and macrophages and cytotoxic T lymphocyte antigen 4 (CTLA-4) ligands are constitutively expressed on regulatory T cells." (PMID 31161238, 2019). "When investigating the plasma concentration of the CXCR3 ligands CXCL9 and CXCL10 in tumor patients treated with anti-PD-1 alone or anti-PD-1 and anti-CTLA-4 antibodies, it was found that the treatment responder group has elevated levels within the first few months after therapy." (PMID 31557787, 2019). "Notably, one patient with MCC refractory to anti-PD-1 and anti-CTLA-4 experienced tumor regression after anti-PD-L1 + radiotherapy." (PMID 31287031, 2019). "Further analysis revealed that other immunomodulatory therapies (such as interferon intratumoral injection, tumor-infiltrating lymphocyte transfusion, and anti-CTLA-4 antibodies in this study) could improve the efficacy of anti-PD-1 antibodies (P=0.023)." (PMID 31662753, 2019). "Perhaps novel approaches based on selective suppression of antigen-specific tumor Treg clones will yield better results than using monoclonal antibodies as functional markers characteristic of the general pool of effector Tregs such as PD-1/PD-L1 or CTLA-4." (PMID 31993063, 2019). "Blockade of CTLA-4 can repair T cell function and enable T cells to exert tumor-killing ability." (PMID 31779642, 2019).
tumor (continued). "Indeed, mAb-mediated inhibition of CD73 increased the anti-tumor efficacy of RT and this synergistic effect was even more apparent upon concurrent CTLA-4-blockade." (PMID 31244820, 2019). "The first generation of antibody-based inhibitory IC enables to restore a correct immune response towards tumor cells, includes antibodies against cytotoxic T-lymphocyte antigen 4 (CTLA4), programmed cell death (PD-1), and programmed cell death ligands (PD-L1/PD-L2)." (PMID 31581738, 2019). "This hypothesis is strengthened by evidence of synergic anti-tumor effects elicited by combining anti-PD-1/CTLA-4 and inhibitors of ADO production or signaling." (PMID 31068926, 2019). "Cancer immunotherapies that inhibit negative immune feedback, such as those targeting programmed cell death 1 (PD1)/programmed cell death-ligand 1 (PDL1) and cytotoxic T-lymphocyte-associated protein 4 (CTLA4), have proven efficacious against several tumor types." (PMID 31300050, 2019). "Checkpoint inhibitors (CPIs) are a promising treatment for haematological malignancies and target immunosuppressive molecules on T-cells such as PD-1 and CTLA-4, thus enhancing anti-tumour immunity, but may also enhance T-cell responses to pathogenic fungi." (PMID 30987351, 2019). "Though not significant, a minor increase in expression of PD-1 and CTLA-4 could be noted, perhaps suggesting an increase in tumor-specific effector T cells and a window for combination therapy with immune checkpoint inhibitors targeting CTLA-4 and/or PD-1." (PMID 30652208, 2019). "CTLA-4 blocking therapy of tumor-bearing mice also reportedly improves IFN-ɤ signaling in T cells." (PMID 32010123, 2019). "In addition to CTLA-4 and PD-1, recent trends shifted to alternative inhibitory receptors and their mechanisms within tumor microenvironments." (PMID 31292525, 2019). "The anti-CTLA-4 blockade is also an effective therapeutic strategy to kill tumor cells." (PMID 30911684, 2019). "Therefore, such synergistic immune responses induced with the assistance of an anti‐CTLA‐4 checkpoint inhibitor are considered an effective approach to inhibit tumor metastasis." (PMID 31763151, 2019). "Therefore, Treg CTLA-4 is a dominant mechanism of immunosuppression that continues to promote inhibition of the anti-tumor response." (PMID 31681327, 2019). "Interestingly, this also resulted in immunity against the secondary exposure to tumor cells, suggesting that the memory component of the immune response can be evoked by anti CTLA-4 antibodies." (PMID 30953535, 2019). "For comparison purposes we verified whether anti PD1 and anti CTLA-4 could prevent MC38 tumor growth by starting the treatment before tumor challenge." (PMID 30764846, 2019). "Notably, the TbethiFoxp3hi Tregs expressed higher levels of helios, CTLA-4 and Ki67 than the Tbet– Foxp3+ Tregs, suggesting that they have been stimulated and activated in the tumor microenvironment." (PMID 30658697, 2019). "In the mouse model of lung adenocarcinoma, refractory to an anti-PD-1 and anti-CTLA-4 mAb combination therapy, the use of oxaliplatin in combination with a low-dose of cyclophosphamide increased the lung CTLs/Treg cell ratio sensitizing the tumor to ICIs." (PMID 30991686, 2019). "CTLA-4 is an important mediator of self-tolerance and tolerance to tumor antigens." (PMID 31244654, 2019). "Additionally, there were significant differences in immunoexpression intensity of CTLA-4 in TCs of the various tumor subtypes (p < 0.0001); specifically, it was more intense in YST, CH and TE, when compared to EC or SE." (PMID 31614500, 2019). "As an immune tolerance checkpoint, CTLA-4 is an effective therapeutic target in tumor patients." (PMID 30678689, 2019). "Inhibitory tumor microenvironment binding inhibitory receptors, such as PD-1, CTLA-4, LAG-3, and TIM-3 on T cells might also cause insufficient response rates of CART cells in certain tumor entities, and therefore impair the immune attack." (PMID 31835562, 2019).
tumor (continued). "Interestingly, the CTLA-4 combination created enhanced CD8 to Treg ratios in the distal tumor, whereas the PD-1 combination yielded improved ratios of CD8 relative to suppressive myeloid stroma." (PMID 31771649, 2019). "Consistent with our prior studies, anti-CTLA-4 resulted in significant tumor growth inhibition." (PMID 31653272, 2019). "CTLA-4 is highly upregulated in the tumor microenvironment (TME), particularly on Tregs." (PMID 30975201, 2019). "The tumor-infiltrating lymphocyte (TIL) population expresses immune checkpoints, programmed cell death 1 (PD-1), which is targeted by pembrolizumab and nivolumab; and cytotoxic T-lymphocyte associated protein 4 (CTLA-4), which is targeted by ipilimumab." (PMID 31337426, 2019). "CTLA-4 inhibitor-mediated anti-tumor activity may therefore extend to secondary lymphoid organs rather than only within the TME." (PMID 30941125, 2019). "Therefore, inhibition of CTLA-4 can shift this balance towards T-cell activation, resulting in destruction of the antigens expressed on tumor cells." (PMID 30975211, 2019). "CTLA-4 blockade using mAb ipilimumab improves the anti-tumor response." (PMID 30884772, 2019). "These immune checkpoint inhibitor therapies restore anti-tumor immune responses by disrupting the interactions between receptors (PD-1 or CTLA-4) on T and NK cells and their corresponding ligands, PD-L1 on tumor cells or CD80/86 on antigen presenting cells, respectively." (PMID 30941308, 2019). "CTLA-4 is known to be constitutively expressed by Tregs, and is considered to promote immune suppression by enhancing their immune-inhibitory function; thus, administration of the anti-CTLA-4 mAb has been demonstrated to effectively treat various tumor types by abrogating Treg activity." (PMID 31134084, 2019). "Both CTLA-4 and PD-1 were originally identified in T lymphocytes, while PD-Ls may be expressed on different tumor cells." (PMID 31214193, 2019). "However, in tumor tissues, CTLA-4 often promotes unwanted repression of anti-tumor immunity in individuals suffering from cancer." (PMID 31061392, 2019). "CD56 is a marker that identifies NK cells; the positive correlation between CD56 RNA in the tumor and the benefit from anti-CTLA4 may suggest that increased NK cell infiltration can enhance anti-CTLA4 efficacy in humans." (PMID 31614774, 2019). "To date, the CTLA-4 antibody ipilimumab, the anti-PD-1 antibodies nivolumab, pembrolizumab, cemiplimab, and the anti-PD ligand-1 antibodies atezolizumab, avelumab, and durvalumab have been approved for a variety of nine tumor entities." (PMID 31653079, 2019). "Studies have shown that the reduction in Tregs cells would prevent the expression of immunosuppressive cytokines or that the targeted therapy against these cytokines, such as CD25, TGF-ß, CTLA-4 and so on, would prevent their functions, thereby controlling tumour growth." (PMID 30893948, 2019). "In particular, antibody-mediated interventions targeting cytotoxic T lymphocyte antigen-4 (CTLA-4) and programmed death receptor-1 (PD-1) on T lymphocytes and the principal ligand (PD-L1) on tumour cells can reverse tumour-induced immunosuppression and induce durable clinical responses." (PMID 31537801, 2019). "Furthermore, combination therapy of PD-1/CTLA-4 signaling blockade resulted in complete protection from metastasis in 50% of treated mice as well as in T cell memory protection against future tumor inoculation." (PMID 31847387, 2019). "Lack of an assembled BCR in pre-treatment tumor tissues was associated with a lack of anti-tumor response to a CTLA-4 inhibitor in metastatic SKCM." (PMID 31138334, 2019). "PD-1 blockade predominantly activates T cells within tumor, and CTLA-4 blockade could help T cell activation and trafficking." (PMID 30975989, 2019).
tumor (continued). "Alternatively, combination therapy of RRV-scFv-PDL1 and therapeutics with very narrow therapeutic indices such as anti-CTLA4 antibody could lead to synergistic anti-tumor activity while reducing immune toxicities reported in current combination therapies." (PMID 31040917, 2019). "Finally, for exhausted signature genes, two inhibitory receptors PDCD1 and CTLA4 were found to be specifically demethylated within tumor-reactive CD8+ T cells." (PMID 31892342, 2019). "Moreover, anti-CTLA-4 combined with IL-15/IL-15Rα enhances the NK cell tumor infiltration, improving the tumor growth control in xenograft murine models of solid tumors." (PMID 32038612, 2019). "Various studies described that tumours infiltrating Treg cells are presumed to be activated by neo-antigens released from tumour cells, are present in high concentrations within tumours and manifest the enhanced expression of suppression-related molecules such as CTLA-4." (PMID 30893948, 2019). "Antibodies to CTLA-4 were the first checkpoint inhibitors with anti-tumor activity." (PMID 31137694, 2019). "As a result, CTLA-4 inhibits T cell activation within secondary lymphoid organs, but PD-1/PD-L1 chiefly regulates T cell function within peripheral tissues and the tumor microenvironment." (PMID 30774597, 2019). "However, the tumor-infiltrated Tregs include heterogeneous subsets of cells expressing different immunosuppressive molecules favoring tumor progression, such as CTLA-4, PD-1, LAG-3, TIM-3, and TIGIT." (PMID 30718502, 2019). "Consequently, the ratios of CTLs to Tregs and to Arg1+ MDSC were significantly enhanced with the triple combination therapy of ML-RR-CDA administration into the flank tumor combined with systemic α-PD-1 and α-CTLA-4." (PMID 31533840, 2019). "We investigated whether carbon ion irradiation combined with dual immune checkpoint blockade therapy (anti-PD-L1 and anti-CTLA-4 antibodies [P1C4]) provides anti-tumor efficacy for both local and distant sites." (PMID 30774761, 2019). "Notably, when using the i.p. route of injection, anti-PD-1 plus anti-Nrp-1 combination had similar effects on tumour progression than anti-PD-1 plus anti-CTLA-4." (PMID 31350404, 2019). "Interestingly, the co-expression of tumor cell-derived CTLA-4 and TIIC-derived CTLA-4 can predict the outcomes of ESCC patients more accurately than each marker alone." (PMID 31771653, 2019). "Currently, research focused on re-establishing suppressed anti-tumor immunity has examined monoclonal antibody (mAb)-based interventions by targeting CTL antigen 4 (CTLA-4) and programmed cell death protein 1 (PD-1) on T lymphocytes and its primary ligand (PD-L1) on tumor cells." (PMID 31323785, 2019). "Overall, we found that the absence of B cells and a tumor which more often classifies as an IL10 regulatory B cell were associated with a lack of response to anti-CTLA4 therapy." (PMID 31138334, 2019). "In addition, radiation therapy also upregulates the expression of T-cell inhibitory proteins such as PD-1 and CTLA-4 on tumor cells that suppress the host immunity." (PMID 31362708, 2019). "Anecdotally, CTLA-4 inhibition with ipilimumab has demonstrated anti-tumor activity in a small series of MCC cases, and is currently being investigated in combination with nivolumab in patients with advanced MCC or virus-associated cancer (ClinicalTrials.gov Identifier: NCT02488759)." (PMID 31287031, 2019). "Similarly, targeting the PI3K pathway in mouse models with PTEN loss by using a selective small molecule inhibitor improved T cell-induced tumor killing and efficacy of immunotherapy with anti PD-1 and anti-CTLA4 treatments." (PMID 31658667, 2019). "Additionally, MAX-10129 demonstrated anti-tumor efficacy in the combinations with an anti-CTLA4 antibody, an IDO inhibitor Epacadostat, a COX-2 inhibitor Celebrex, and the cytotoxic cisplatin." (PMID 31151293, 2019). "Combined blocked of TIM-3 blockade with either CTLA-4 or PD-1, has shown anti tumor activity." (PMID 30740266, 2019).